CD44 (CD44 molecule (IN blood group))
Diseases named in the same sentence as CD44 in open-access papers (continued):
Sharing a sentence is not in itself a finding about the gene and the disease.
cancer (continued). "This group used xenotransplantation to identify a tumourigenic sub-population of cancer cells isolated from human primary pancreatic cancer tissue expressing CD44, CD24, and epithelial-specific antigen (ESA)." (PMID 33799834, 2021). "Antibodies (mAbs) to CD44 are being investigated for cancer therapy, for example, mAb U36 specific to CD44v6 in HNSCC and mAb VFF18 specific to CD44v6 in human squamous cell carcinomas." (PMID 34946546, 2021). "Another study suggested that cholesterol promoted the translocation of CD44 into lipid rafts and attenuated CD44-Ezrin binding, a process that is essential for cell migration and cancer metastasis." (PMID 33905408, 2021). "As CD133 and CD44 are two important CSC surface markers in several types of cancer, CIH exposure significantly enhanced the percentage of CD44+CD133+ subsets in NSCLC cells evidenced by flowmetry analysis." (PMID 33596919, 2021). "Changes in the tissue expression patterns of different isoforms of CD44 can impair epithelial-mesenchymal interactions and contribute to the characteristic functional and structural disorganization found in cancer." (PMID 33505471, 2021). "The cancer stem cell marker CD44 scored positive in a small number (n = 8) of (CD24-negative) objects." (PMID 33801459, 2021). "This corroborates with our in vitro data in which 4bt considerably decrease cancer stem cells (CSC) represented by CD44+/CD24- population." (PMID 34548908, 2021). "CD44 have been identified as cancer stem cell markers for isolating and enriching cancer stem cells." (PMID 34408983, 2021). "By click reaction, a PEGylated liposome was engineered in such a way to carry a cancer stem cell (CSC) marker CD44-specific aptamer onto it." (PMID 34575825, 2021). "CD44-positive GC cells are reported to contribute to increased resistance to radiation- or chemotherapy-induced cancer cell death." (PMID 34575403, 2021). "13R,20-diHDHA reduced the populations of CD44high/CD24low and aldehyde dehydrogenase (ALDH)-positive cells and the expression levels of the cancer stemness-related self-renewal genes, Nanog, Sox2, Oct4, c-Myc, and CD44." (PMID 33804152, 2021). "miR-34a inhibits metastasis by directly repressing CD44, a cancer stem cell marker that has been considered to indicate a more mesenchymal phenotype of human PCa cells." (PMID 34503302, 2021). "In vitro studies confirmed internalization by CD44 overexpressing MCF-7 cells as an on-demand PTT platform to elicit cancer cell ablation for potential targeted cancer therapy." (PMID 33804239, 2021). "In both inflammatory disease and cancer patients, proteolytically generated soluble CD44 levels in the circulation are much higher." (PMID 34796172, 2021). "As cancer stem cells are known to be more resistant to cytotoxic treatment, we also investigated the expression of the stem cell marker CD44 in 2D and 3D cultures and in response to 5-FU treatment." (PMID 33395433, 2021). "The CD44 antigen has been implicated in modulating tumorigenesis in many cancer types in which high expression of this CD44 increases cancer cells proliferation, motility and survival as well as promoting cancer metastasis." (PMID 34301218, 2021). "Not only do normal stem cells express high levels of CD44, but CD44 is also highly expressed by cancer cells and serves as a cell surface marker facilitating their isolation." (PMID 33822772, 2021). "CD44 activation by HA in cancer cells induces transcriptional and epigenetic changes that stimulate signaling pathways controlling invasiveness and metastasis, chemoresistance, and stemness." (PMID 33810348, 2021). "RP11‐89 was significantly correlated with the expression of CD44, CD70 and LAGLS9 in pan‐cancers and was significantly associated with the abundance of activated CD4 T cells, activated CD8 T cells and effector memory CD4 T cells in pan‐cancers." (PMID 33797188, 2021).
cancer (continued). "CD44 isoform switching in cancer cells as well as normal cells happens in response to some stimuli like oxidative stress, activation of signal transduction pathways especially MAP kinases, epigenetics or upon activation of resting lymphocytes." (PMID 34257584, 2021). "Based on differences in western blot patterns of cancer cell lysates, the four anti-CD44 mAbs separated into three distinct categories that include P4G9, P3D2, and P3A7, and P3G4." (PMID 33891595, 2021). "HMW–HA is also being developed in experimental models and clinical trials to target CD44 for both imaging and delivery of therapeutics to cancer stem cells." (PMID 34827550, 2021). "DGC5 (DiGeorge syndrome critical region gene 5) contributes to cancer cell stemness-like properties by regulating miR-330-5p/CD44 in NSCLC." (PMID 34715859, 2021). "Multiple previous studies showed that CD44 played a significant role in regulating cell invasion, migration, and cancer stemness in various tumors." (PMID 34681583, 2021). "The surface expression of MIF coreceptor CD74 and CD44, which promote downstream signaling pathways for cancer cell proliferation and migration, were decreased in rSmeg-hMIF-hIL-7 compared with all other groups." (PMID 34389619, 2021). "There is also increasing evidence that CD44 can be considered a marker of cancer stem cells in breast, pancreas, and colorectal cancer, contributing to maintaining and initiating tumors." (PMID 34360868, 2021). "Of these, aldehyde dehydrogenase (ALDH) has been a highly specific cancer stem cell marker, specifically when co-analyzed with CD44." (PMID 35047489, 2021). "Expression of cancer stem cell markers (CD44, ALDH1, CD133 and YAP1) and activation of oncogenes varied among the cell lines." (PMID 34162421, 2021). "The differentiation 44 (CD44) cluster, a hyaluronic acid receptor, is expressed in many different types of cancer-initiating cells, cancer stem cells (CSCs), and rapidly proliferating cells." (PMID 34208132, 2021). "CD44 has a tremendous binding affinity to HA, which attracts our attention to develop HA-based NPs leading to an increase in the affinity of NPs to cancer cells and CSCs and selective toxicity due to HA-CD44 receptor-mediated endocytosis." (PMID 33672756, 2021). "Our in vitro data shows that Reg4-CD44ICD signaling regulates proliferation and survival of the cancer stem cells, hence providing a unifying explanation for poor clinical outcomes with Reg4 and CD44/CD44ICD." (PMID 33659040, 2021). "The majority of head and neck tumours expresses CD44, a cancer stem-like antigen, for which targeting moAbs are currently under investigation in phase 1 clinical trials." (PMID 33836238, 2021). "HA and its major cell surface receptor, CD44, have been suggested to be important cellular mediators influencing prognosis in several malignant tumors." (PMID 35154001, 2021). "Chemoresistant cancer cells possess stem-like characteristics, such as the ability to form spheres and high expression of cancer stem cell-like surface markers CD44/CD133." (PMID 34439378, 2021). "Lipid rafts, enriched with sphingolipids and cholesterol, regulated the interaction between CD44 and hyaluronan, mediating cancer cell migration." (PMID 35047398, 2021). "In this study, we used metastatic organ-derived cell lines to investigate the effects of CD44 expression on cancer progression across different metastatic niches." (PMID 34579762, 2021). "CD44 can be used as a cell surface marker in order to identify cancer stem-like cells (CSCs) in many cancer types." (PMID 33780455, 2021). "It has been found that the main ligand of CD44, hyaluronan, is a major constituent of the cancer stem cell niche maintaining the CSC phenotype, which has a substantial impact on the stemness properties of CSCs." (PMID 34830890, 2021). "CD133 and CD44 expression levels were checked in cancer cells and cancer stem cells flow cytometrically." (PMID 34071008, 2021).
cancer (continued). "Cancer cells with CD44+ on their membranes have stem cell‐like characteristics as well as the ability to self‐renew." (PMID 34841662, 2021). "Taken together, CD44 plays a crucial role in cancer metabolism, including the alteration of amino acids, glucose, and redox metabolism." (PMID 33726850, 2021). "It has been supported by many studies that CD44 is an important biomarker of cancer stem cells (CSC) and is particularly important in CSC microenvironment communication." (PMID 34599251, 2021). "After the CD133+/CD44+ cells with cancer stem cell (CSC) characteristics were isolated and identified by flow cytometry, lncRNA TUG1 expression was quantified by quantitative real-time PCR." (PMID 34858502, 2021). "Pluripotency genes, POU5F1 and NANOG, displayed approximately 2–3 fold increases in their protein expression in HT29 cells grown on colorectal PDS compared to 2D, whereas other cancer stem cell markers, such as CD44 decrease by approximately 90%." (PMID 33356003, 2021). "The HA receptor CD44 is found sparsely on the surface of epithelial, hematopoietic, and neuronal cells, and is abundantly overexpressed in various cancer cells." (PMID 34959321, 2021). "On the contrary, increasing evidence is recently emerging of a controversial and isoform-specific role of CD44 in cancer." (PMID 34018387, 2021). "The changes of resistance can be used as a signal to evaluate the number of cancer cells and the expression level of CD44." (PMID 34360949, 2021). "Although CD44 has traditionally been used to monitor cancer metastasis, recent studies from Gao and coworkers showed that its expression fluctuates during metastatic progression." (PMID 34579762, 2021). "CD44 is a well-known cancer stem cell marker and is upregulated in certain cancer cell subpopulations." (PMID 34439211, 2021). "Hyaluronic acid (HA), a major component of the extracellular matrix (ECM) expressed by both stromal and cancer cells, is the main ligand for CD44, and an HA-binding domain is present in all CD44 isoforms." (PMID 34439211, 2021). "The purpose of this study was to explain the relationship between CD44+ cancer stem cell expression with the histopathological type of NPC." (PMID 34804499, 2021). "We have confirmed the selective delivery capability of DDM (at IC50 doses) into cancer cells by investigating HA, CD44, and FR-α expression levels." (PMID 34771733, 2021). "CD44 expression is one example of how a surface protein is shared on CTCs and EVs, in which the same protein interactions can lead to different roles in cancer progression." (PMID 34571870, 2021). "We show here that BMP4 acts as a potent differentiation factor and prevents cancer stemness by inhibiting tumorsphere formation and reducing CD44+/CD24− CSC numbers in TNBC." (PMID 33649296, 2021). "CD44 is known as a pivotal marker for cancer stem cells, and an overexpression in cancer cells with a suspected exhibition of highly malignant and therapeutic resistance properties is reported." (PMID 33009929, 2021). "CD44 promotes metastasis, chemoresistance, and stemness in different types of cancer and is a target for the development of new anti-cancer therapies." (PMID 33810348, 2021). "CD44 antibodies and blockade of the HA-CD44 balance offer therapeutic interventions to effectively impair the properties of CSCs among various cancers." (PMID 34774101, 2021). "CSCs and non-CSCs subpopulations were counted by flow cytometry using the cancer stem cell markers CD44 and CD24." (PMID 34242345, 2021). "All three selectins have been shown to interact with CD44 in order to facilitate both normal leukocyte adhesion and rolling as well as cell–cell adhesion in pathological conditions, such as cancer metastasis." (PMID 34829810, 2021).
cancer (continued). "Intriguingly, it has been shown that both Ovol2 and Zeb2 modulate cellular plasticity by fine-tuning the hybrid epithelial/mesenchymal states of Cd44+ cancer cells." (PMID 33989778, 2021). "In order to examine the stemness of these cells, colonies of these cells were excised under a microscope and dispersed by trypsin/EDTA treatment, and the presence of cancer stem cell markers (CD44, CD133, Oct3/4, ALP) was examined in these free cells." (PMID 34115931, 2021). "The four characterized mAbs bind to a variety of CD44 isoforms in cancer cell lysates, indicating that the targeted amino acids region of these isoforms, which is in the N-terminal conserved region, is unglycosylated in the native state." (PMID 33891595, 2021). "Expression of the prominent CSC markers CD133, CD44, and Nestin as well as successful formation of spherical cancer organoids confirmed a CSC-like phenotype." (PMID 33925297, 2021). "CD44 is believed to undergo functional and structural alterations through malignant transformation, which contributes to the detachment of cancer cells from their original site, which then go on to invade the surrounding tissues." (PMID 34944493, 2021). "Curcumin is known to inhibit the proliferation, invasion, and desiccation of CD44+/CD133+ cancer cells." (PMID 33859758, 2021). "Accumulative of previous studies showed that CD44 can regulate cancer cell migration/invasion, angiogenesis, proliferation, and metastasis." (PMID 34681583, 2021). "TNBC is enriched in cancer stem cell populations, and CSCs are distinguished from other cancer cells by the expression of cell surface markers CD44+/CD24− and overexpression of octamer-binding transcription factor 3/4 (OCT-3/4)." (PMID 34830320, 2021). "Blocking antibodies to SPP1 and its specific receptors CD44 showed an inhibitory role in cancer cell migration." (PMID 34676217, 2021). "Many studies have demonstrated that HA-based nanoparticles can undergo rapid internalization into various cancer cells through both enhanced permeability and retention effect and CD44-mediated endocytosis." (PMID 33504007, 2021). "HA, also known as hyaluronan, is a naturally occurring non-sulfated glycosaminoglycan, with characteristics such as biocompatibility, non-immunogenicity, and biodegradability, making it an ideal material for targeting CD44+ cancer cells." (PMID 33557143, 2021). "It has been reported that the activation of CD44 by its ligand promotes cancer stem cell-like phenotypes in GBM and increased therapeutic resistance." (PMID 34301218, 2021). "Though rare, CTCs with tumorigenic ability mirror the expression of cancer stem cells, CD44+/CD24lo35,36, and supports their prognostic value." (PMID 34211050, 2021). "In mechanism, the invasive and metastatic growth of cancer cells can be mediated by the interaction between CD44 on the cell surface and extracellular matrix components such as hyaluronic acid and then induce changes in the cytoskeleton of cancer cells." (PMID 35082668, 2021). "P-selectin binds to CD44 and promotes the capture of vascular endothelial cells and cancer cells by leukocytes." (PMID 34575403, 2021). "In our study, cancer stemness markers such as CD44, Nanog, EpCAM showed increased expression in sorafenib-resistant HCC cells." (PMID 34473785, 2021). "The expression of CD44 has been correlated with the EGFR level in a variety of cancer, and their expression is positively regulated reciprocally." (PMID 34207383, 2021). "Autophagic flux impairment induced a high expression of CD44 and thus induced mitochondrial dysfunction, oxidative stress and cancer cell death." (PMID 34440579, 2021). "CD44 is the receptor for hyaluronic acid and a transmembrane glycoprotein that is expressed on cancer stem cells." (PMID 34207884, 2021).
cancer (continued). "The interaction of OPN with cluster of differentiation-44 (CD44) mediating several signaling network participates in cancer skeletal metastasis through regulating cell–matrix interactions." (PMID 35154001, 2021). "The anti-glial fibrillary acidic protein (GFAP) antibody was used as a marker of glial cells (mouse glial cells and U87 cells), the anti-neuronal nuclei (NeuN) to mark the neurons, and the human anti-CD44 was used as a cancer cell marker." (PMID 34069377, 2021). "Hyaluronic acid (HA) is a water-soluble mucopolysaccharide, which is a ligand specifically binding to CD44 overexpressed in cancer cells." (PMID 34796163, 2021). "It was observed that cancer stem cells with CD44+/CD24− markers was substantially reduced despite the increase in the presence of cancer stem cell population with this phenotype in chemically defined medium of TNBC cells." (PMID 34873206, 2021). "Eliaz and Szoka provided evidence of the influential delivery of chemotherapeutic agents to cancer cells highly expressing CD44 by HA-modified liposomes." (PMID 34944493, 2021). "CD44, a transmembrane glycoprotein, participates in many physiological processes in cancer, including angiogenesis, cell proliferation, and apoptosis." (PMID 33986244, 2021). "The CD44 exists in various isoforms and gain much importance due to involvement in the pathogenesis of cancer." (PMID 34513617, 2021). "We have found that compound 1 significantly decreased the number and percentage of CD15s+ cells within three subpopulations: CD44+CD24− cancer stem cells, CD44− epithelial cells, and CD44+CD24+ cells that exhibit mesenchymal and epithelial features." (PMID 34206154, 2021). "The CD44 exists in various isoforms and regulate the cell survival signaling pathways in a variety of cancers." (PMID 34513617, 2021). "In accordance with this result, BMP2 increased the expressions of mRNA for the cancer stem cell markers CD44 and c-KIT." (PMID 34360647, 2021). "In vitro CD44-positive cancer cells HT-29 induced OPN expression in THP-1 cells in transwell co-culture system." (PMID 34209679, 2021). "The data indicate significance of the CD24 vs. CD44 expression pattern on various cancer cells and attribute early progenitor/stem cell properties to the CD44+/CD24- population." (PMID 34019593, 2021). "Researchers have taken advantage of the ability of HA to target and bind to CD44 in targeting CD44-overexpressing cancer cells." (PMID 34944493, 2021). "In total, we identified 341 up-regulated genes, including CD24 and CD44, and 138 down-regulated genes in CSCs from both primary cancers." (PMID 33995647, 2021). "The CD44 essential receptor protein involves in cancer cell growth, survival, and metastasis in the majority of cancer." (PMID 34513617, 2021). "While FP shows a lower proliferation than CP, its cancer cells express high levels of two CSC markers (CD44, CD133) as well as MMP14." (PMID 33672734, 2021). "The cell surface proteins CD133, CD24 and CD44 are putative markers for CSC populations in colon cancer, which are associated with aggressive cancer types and poor prognosis." (PMID 34837915, 2021). "The increased CD44 protein level in serum can be an indicator of tumor burden and metastasis in several types of cancer, such as breast, gastric, and colon, and hence it can be used as a biomarker." (PMID 34695934, 2021). "Cluster of Differentiation 44 (CD44) is used as a cell surface marker in order to identify cancer stem-like cells (CSCs) in many cancer types." (PMID 33726850, 2021). "Its receptor, CD44, is highly expressed in several cancer types, therefore it is a potential target for cancer-targeting NPs." (PMID 34307319, 2021). "Considering the fold changes of the cancer stem cell biomarkers, we chose CD44 as our potential target." (PMID 35071232, 2021). "These exosomes increased CD44 expression in HPMCs, which facilitated cancer invasion by inducing the HPMCs to secrete matrix metalloproteinase-9 (MMP9)." (PMID 34680456, 2021).